ACADL (acyl-CoA dehydrogenase long chain)
Diseases named in the same sentence as ACADL in open-access papers (continued):
Sharing a sentence is not in itself a finding about the gene and the disease.
Cirrhosis (1 paper, 2023). A chronic disorder of the liver in which liver tissue becomes scarred and is partially replaced by regenerative nodules and fibrotic tissue resulting in loss of liver function. "According to the presence of cirrhosis, HCC patients were divided into 2 groups and the patients with stiffer hepatic background had lower ACADL expression (p < 0.01)." (PMID 37151879, 2023).
liver cancer (1 paper, 2023). An epithelial or non-epithelial malignant neoplasm that arises from the liver. "Liver cancer cells on high matrix stiffness at 16 kPa had increased free fatty acid levels in the media (p < 0.01) and markedly downregulated mRNA and protein levels of ACADL compared with the control group (p < 0.01)." (PMID 37151879, 2023).
osteoarthritis (1 paper, 2024). A noninflammatory degenerative joint disease occurring chiefly in older persons, characterized by degeneration of the articular cartilage, hypertrophy of bone at the margins and changes in the synovial membrane. "It has been shown that chondrocytes from patients with osteoarthritis exhibit incomplete β-oxidation of fatty acids compared to healthy individuals and are accompanied by mitochondrial damage in cell populations, which may be associated with the downregulation of ACADL expression." (PMID 38292759, 2024).
sarcomatoid mesothelioma (1 paper, 2023). A diffuse malignant mesothelioma arising from the pleura and less often the peritoneum. "In particular, ACADL and subunits of ATP synthase are highly expressed in invasive rat mesotheliomas, as well as in more aggressive human sarcomatoid mesothelioma cells, which have more active FAO, electron chain transport and ATP synthesis, supporting their growth and invasiveness." (PMID 37297007, 2023).
tumor (24 papers, 2015 to 2025). "A recent study revealed that loss of ACADL in HCC cells promoted tumor progression by regulating the PTEN pathway under hypoxia conditions." (PMID 32219176, 2020). "In addition to the dramatic changes observed in ACADL associated with tumor invasiveness, we also identified another protein involved in the mitochondrial translation machinery, i.e., TUFM." (PMID 37297007, 2023). "In FAO, ACSL3 inhibition with enhanced MGF and ACADL regulating Hippo/YAP pathway are anti-tumor immunity strategies." (PMID 38841622, 2024). "In both H1299 and A549, the volume of tumor formation in ACADL groups was about 0.1 times (P < 0.001) compared to that in Control group." (PMID 38402174, 2024). "More importantly, we found that ACADL exerts an anti-tumor effect by promoting the phosphorylation of YAP and limiting its nuclear translocation." (PMID 38402174, 2024). "To investigate the tumor-suppressive role of ACADL in NSCLC, we first detected the expression of ACADL in four NSCLC cell lines (H292, H1944, H1299 and A549) and ACADL protein expression in H1299 and A549 was lower than that in H292 and H1944." (PMID 38402174, 2024). "In summary, our findings demonstrate the tumor-suppressive role of ACADL in NSCLC by enhancing the nuclear translocation of YAP." (PMID 38402174, 2024). "We observed robust E-cadherin expression in ACADL overexpressing tumor tissues, which was partially attenuated by XMU-MP-1 treatment." (PMID 38402174, 2024). "And XMU-MP-1 effectively counteracted the inhibitory effect of ACADL by 0.3 times on the tumor volume (P < 0.01)." (PMID 38402174, 2024). "The role of Acyl-CoA dehydrogenase long chain (ACADL) in different tumor types had different inhibiting or promoting effect." (PMID 38402174, 2024). "Collectively, these findings support the notion that ACADL functions as a tumor suppressor in NSCLC." (PMID 38402174, 2024). "Long-chain acyl-CoA dehydrogenase (ACADL) as an enzyme that regulates β-oxidation is a promising target for regulating Hippo/YAP pathway to confer anti-tumor imunity." (PMID 38841622, 2024). "Consistently, similar experimental results were observed in the xenograft tumor model where XMU-MP-1 partially counteracted the inhibitory effect of ACADL on tumor growth rate." (PMID 38402174, 2024). "The study reveals that ACADL prevents tumor immune evasion by inhibiting YAP and subsequently suppressing PD-L1 expression." (PMID 37569866, 2023). "Collectively, these results suggested that YAP was activated in tumor cells by stiff substrates and consequently induce the repression of ACADL transcription via YAPTEAD4 complex binding to ACADL gene promoter." (PMID 37151879, 2023). "We explored the synergistic predictive value of collagen content and ACADL expression in tumor tissue on prognosis." (PMID 37151879, 2023). "Although previous study has indicated that the tumor-suppressive effects of ACADL through inhibiting the Hippo/YAP signaling." (PMID 37151879, 2023). "Examination of ACADL expression by IHC in the four tumor models revealed pronounced differences with the level of invasiveness." (PMID 37297007, 2023). "ACADL showed higher mRNA and protein levels in tumor tissues in BAPN group than PBS control group (p < 0.01)." (PMID 37151879, 2023). "In contrast, the mildly invasive F4-T2 and moderately invasive F5-T1 tumors exhibited a weak, homogeneous distribution of ACADL expression within the tumor tissues." (PMID 37297007, 2023). "Conversely, ACADL is upregulated in esophageal squamous cell carcinoma cell lines and tumor tissue and predicts worse outcomes." (PMID 33413672, 2021). "The results confirmed that CPEB3 and ACADL were significantly related to tumor immunity: CPEB3 was related to the content of B cells and neutrophil; ACADL was related to the infiltration of B cells, CD8+ T cells, CD4+ T cells, macrophages, and dendritic cells." (PMID 33719338, 2021).
tumor (continued). "Collectively, these studies suggest that ACADL functions as a tumor suppressor in HCC through regulating YAP activation." (PMID 32219176, 2020). "More importantly, ACADL-suppressed tumor growth in nude mice was diminished after XMU-MP-1 exposure." (PMID 32219176, 2020). "The data revealed that tumor growth were remarkably suppressed in ACADL re-expressed groups compared with control groups, and the ACADL re-expressed groups had much lower tumor weight than the control groups at the end of observation." (PMID 32219176, 2020). "Moreover, IHC analysis revealed a notable decrease in the expression of proliferative proteins Ki67 and PCNA in ACADL overexpressing tumor tissues, which was partially reversed in the XMU-MP-1 treatment group." (PMID 38402174, 2024). "Furthermore, the inhibitory effect of ACADL on NSCLC cells was confirmed in a xenografted tumor model, where ACADL overexpressing cells formed tumors at a significantly slower rate compared to the Control group in vivo." (PMID 38402174, 2024). "Previous study has found that ACADL played a tumor-suppressor role in HCC8,9." (PMID 37151879, 2023). "Moreover, ACADL expression appeared heterogeneous within the tumor, with some areas showing intense staining in external parts of the tumor, as shown on high magnification views." (PMID 37297007, 2023). "The expressions of CPEB3 and ACADL were downregulated in tumor tissues." (PMID 33719338, 2021). "Long-chain acyl-CoA dehydrogenase (ACADL) is a mitochondrial enzyme that catalyzes the initial step of fatty acid oxidation, but the role of ACADL in tumor biology remains largely unknown." (PMID 32219176, 2020). "Notably, the tumor stage plot analysis from TCGA database showed ACADL expression was gradually decreased as HCC progressed to a higher clinical stage." (PMID 32219176, 2020). "However, our studies using gain of function strategies uncovered that ACADL possessed tumor-suppressive effects on HCC cells under normal conditions." (PMID 32219176, 2020). "ACADL, a member of the acyl-CoA dehydrogenases superfamily, is responsible for catalyzing the initial step for the β-oxidation of long-chain fatty acyl-CoAs and has recently been reported to play roles in tumor progression." (PMID 32219176, 2020). "However, the role of ACADL can vary across different tumor types." (PMID 38402174, 2024). "Linked to the tremendous increase in ACADL, the greater abundance and expression of the two subunits of isocitrate dehydrogenase tend to confirm previous observations regarding the central role of the TCA cycle in metabolic reprogramming and tumor invasiveness." (PMID 37297007, 2023). "In fact, the low expression of CPEB3 and ACADL could be associated with higher tumor grade but could not be associated with gender, tumor stage, or TNM." (PMID 33719338, 2021). "ACADL was able to inhibit the movement of YAP into the nucleus, thereby exerting an inhibitory effect on tumor growth." (PMID 38402174, 2024). "In the present study, we found significant downregulation of ACADL expression by comparing the expression profiles of NSCLC and adjacent tumors, and demonstrated that overexpression of ACADL can inhibit tumor progression in vitro and transplanted tumor models." (PMID 38402174, 2024). "Furthermore, it has been reported that the loss of ACADL enhanced tumor growth by inhibiting the expression of the suppressor gene phosphatase and tensin homolog deleted on chromosome ten PTEN) in vivo; therefore, the loss of ACADL is correlated with poor clinical prognosis of HCC patients." (PMID 35844514, 2022). "Clinical samples showed significant downregulation of the following genes: CPT2, ACAA2, HPGD and ALDH3A2, while the expression of ENO2, TDO2, CPOX, ACADL and PTPRG was significantly upregulated in the tumor tissue (p < 0.01)." (PMID 36230866, 2022).
tumor (continued). "Otherwise, actinin alpha 1 (ACTN1) expression, acyl-CoA dehydrogenase Long-chain (ACADL)/YAP, and YAP/Forkhead Box M1 (FOXM1) are proposed targets for preventing tumor growth and early recurrence of HCC." (PMID 36033517, 2022). "ACADL is downregulated in HCC and overexpression results in reduced in vitro cell growth and in vivo tumor size." (PMID 33413672, 2021). "In particular, the fatty acid metabolism related genes, such as FATP2, ACADL, CPT1A, and so on, were elevated in PTC specimens compared to that in para-tumor specimens." (PMID 34976793, 2021). "Intriguingly, the low ACADL expression group had increased serum AFP levels (P = 0.01), larger tumor size (P = 0.036), promoted vascular invasion (P = 0.004), and recurrence (P = 0.002)." (PMID 32219176, 2020). "Then the expression of ACADL and YAP activation were examined in HCC organoids and original tumor tissues." (PMID 32219176, 2020). "According to the immunohistochemical results of ACADL staining in tumor sections, the total 139 HCC samples were divided into low ACADL expression group (n = 69) and high expression group (n = 70)." (PMID 32219176, 2020). "A previous study suggested ACADL could inhibit the PDL1 transcription and promote the tumor cell survival in chemotherapeutic process." (PMID 38402174, 2024). "The expression levels of ACADL, ACADS, ACADSB, ALDH6A1, ETFDH, and GCDH were found to be lower in tumor samples compared to normal samples, whereas the expression levels of CCNB1 and CDK1 were observed to be higher in tumor than in normal samples." (PMID 37994323, 2023). "Finally, the key tumor suppression axis (hsa_circ_0077210/hsa-miR-92b-3p/CPEB3 and ACADL) was constructed." (PMID 33719338, 2021). "In summary, our findings identify the tumor-suppressive effects of ACADL through inhibiting the Hippo/YAP signaling, and provide proof of principle that inhibiting YAP activation will be a viable strategy for HCC patients with low ACADL expression." (PMID 32219176, 2020). "The results showed that verteporfin markedly reduced tumor growth in control groups, whereas the tumors with re-expressed ACADL had not responsive to verteporfin treatment, which support the data in HCC organoids." (PMID 32219176, 2020). "Matrix stiffness has been documented to regulate the expression of key tumor genes through various signaling pathways, including the integrin β1/Piezo1 activation/Ca2+ influx pathway, RhoA/ROCK pathway, YAP-POSTN-integrin mechanotransduction signaling, and YAP/TEAD4/ACADL axis." (PMID 40867005, 2025).
cancer (8 papers, 2014 to 2024). A tumor composed of atypical neoplastic, often pleomorphic cells that invade other tissues. "Next, to further address if YAP is involved in ACADL-regulated cancer cell proliferation, we applied XMU-MP-1, an activator of Hippo pathway, which can promote YAP nuclear translocation and reactivate YAP12." (PMID 32219176, 2020). "A recent paper demonstrated that the expression of ACADL was downregulated by HIF-1α under hypoxic conditions in human HCC cells, and decreased ACADL expression led to cancer progression through promoting accumulation of unsaturated fat9." (PMID 32219176, 2020). "Consequently, CPEB3 and ACADL might inhibit the occurrence of HCC through inhibiting a variety of cancer signaling pathways related to tumorigenesis and progression." (PMID 33719338, 2021). "Although studies have shown the correlation between ACADL and progression of some human cancers, the molecular mechanisms by which ACADL regulates HCC growth and progression are not well understood." (PMID 32219176, 2020).
infection (2 papers, 2010 to 2022). The state of being infected such as from the introduction of a foreign agent such as serum, vaccine, antigenic substance or organism. "However, several other FAO enzymes, such as ACADL, ACADVL, and HADH, showed high levels in response to infection, which supports increased FAO." (PMID 36453897, 2022).
ACADL also shares sentences with these, for which no sentence is quoted: (VLCAD) deficiency (7 papers); heart failure (2); Metabolic disorder (2); (MCAD) deficiency (1); acute kidney injury (1); CACT) deficiency (1); cardiomyopathy (1); cardiovascular disease (1); central obesity (1); chronic gastritis (1); endometriosis (1); epithelioid mesothelioma (1); heart diseases (1); hyperglycaemia (1); Infertility (1); influenza (1); lactic acidosis (1); LCAD) deficiency (1); lipidosis (1); lung adenocarcinoma (1); melanoma (1); metastatic cancer (1); non-alcoholic fatty liver disease (1); non-small cell lung carcinoma (1); porphyria (1); type 2 diabetes (1).